SUSD3 (sushi domain containing 3)
Description:
May play a role in breast tumorigenesis by promoting estrogen-dependent cell proliferation, cell-cell interactions and migration.
Synonyms: MGC26847
Tractability: Antibody: UniProt places it where antibodies can reach, with high confidence; its Gene Ontology location is reachable by antibodies, with high confidence; UniProt predicts a signal peptide or a membrane-spanning region. PROTAC: ubiquitination databases record sites on it.
Gene: Protein-coding gene on chromosome 9 (93,058,688 to 93,085,138, forward strand). Ensembl gene ENSG00000157303.
Subcellular location: Cell membrane
Gene Ontology:
Molecular function: protein binding
Cellular component: plasma membrane
Genetic constraint (gnomAD): Loss-of-function variants: 17 observed, 19.12 expected, observed/expected ratio (o/e) 0.89, 90% interval 0.61 to 1.33. The upper end of that interval is the gene's LOEUF score, 1.33, which puts it in group 5 of 6, group 1 being the genes least tolerant of losing a copy. Missense variants: 305 observed, 334.64 expected, observed/expected ratio (o/e) 0.91, 90% interval 0.83 to 1. Synonymous variants: 137 observed, 138.44 expected, observed/expected ratio (o/e) 0.99, 90% interval 0.86 to 1.14.
Homologues: Orthologues: chimpanzee SUSD3 (99% identical), mouse Susd3 (64% identical), rat Susd3 (63% identical), guinea pig SUSD3 (62% identical), pig SUSD3 (62% identical), macaque SUSD3 (60% identical), dog SUSD3 (57% identical), tropical clawed frog susd3 (37% identical). Paralogues in human: CSMD1 (20% identical), CSMD2 (19% identical), SEZ6L2 (19% identical), SVEP1 (19% identical), CSMD3 (18% identical), SEZ6 (18% identical), CFH (17% identical), SEZ6L (17% identical), CR1 (15% identical), SUSD4 (15% identical), CR2 (15% identical), C4BPA (14% identical), and 27 more.
Diseases named in the same sentence as SUSD3 in open-access papers:
SUSD3 is named in the same sentence as 16 diseases in open-access papers, as found by Europe PMC text mining. Sharing a sentence is not in itself a finding about the gene and the disease. The quoted sentences say what the papers report.
breast carcinoma (13 papers, 2014 to 2026). "Recognized as a novel susceptibility marker, SUSD3 presents a promising target for antibody-based therapies, offering a potential approach for the prevention, diagnosis, and treatment of breast cancer." (PMID 40191190, 2025). "The possibility of SUSD3 as a prognostic and diagnostic marker of breast cancer was investigated in several studies, including a DNA microarray analysis, a pathological study and an epidemiological study." (PMID 35976950, 2022). "SUSD3, a novel gene within the E2/ER signaling pathway, is particularly associated with immune modulation and has been identified as a potential biomarker for the therapeutic sensitivity of aromatase inhibitors (AIs) in breast cancer treatment." (PMID 40191190, 2025). "The diseases associated with SUSD3 were explored through the OpenTarget platform, where a bubble plot revealed a significant correlation between SUSD3 and various malignancies, including breast cancer and clear cell renal carcinoma, among others." (PMID 40191190, 2025). "The risk score of breast cancer prognosis was determined with the following formula: RiskScore = 0.629*ANO6 + 0.147*CELSR3 + 0.381*CLDN7+ 0.273*EPB41L4B-0.357*FAM166B -0.843*GPLD1–0.202*LEF1–0.202*PPARG -0.127*SUSD3." (PMID 34364397, 2021). "Previous studies have highlighted SUSD3 as a critical mediator of estrogen signaling in breast cancer cells, suggesting its involvement in estrogen-dependent metastatic processes." (PMID 40191190, 2025). "In vitro experiments demonstrated that SUSD3 knockdown in breast cancer cell lines significantly reduced proliferation and migration." (PMID 40191190, 2025). "The results of our experiments demonstrated a marked reduction in breast cancer cell proliferation following SUSD3 silencing." (PMID 40191190, 2025). "At present, there are few reports on Sushi domain-containing protein 3 (SUSD3), mainly focusing on the mechanism of SUSD3 in the occurrence and development of breast cancer." (PMID 38167056, 2024). "Experiments have shown that SUSD3 has a higher level of expression in estrogen receptor (ER) -positive breast cancer cells, and estrogen treatment can further increase its expression." (PMID 38167056, 2024). "Prognostic significance of faciogenital dysplasia 3 (FGD3), SUSD3, and other single-gene proliferation markers was evaluated in breast cancer and The Cancer Genome Atlas (TCGA) cohorts." (PMID 32913979, 2017). "Notably, the expression of SUSD3 was markedly elevated in breast cancer compared to normal breast tissue." (PMID 40191190, 2025). "Notably, SUSD3 has shown strong potential as a prognostic marker in breast cancer, where its high expression correlates with poor prognosis, emphasizing its importance in the clinic." (PMID 40191190, 2025). "SUSD3 has been reported as one of the potential biomarkers for the prognosis of breast cancer." (PMID 38167056, 2024). "Consequently, numerous studies have indicated that SUSD3 could serve as a novel tumor marker, capable of predicting therapeutic outcomes and playing a pivotal role in forecasting both the prognosis of breast cancer and the efficacy of adjuvant therapies." (PMID 40191190, 2025). "Therefore, controlling macrophage populations could provide a means to elucidate the role of SUSD3 in breast cancer patients, potentially altering prognostic outcomes." (PMID 40191190, 2025). "In this study, SUSD3 was knocked down in MCF-7 cells to observe its effects on the proliferation and migration of breast cancer cells." (PMID 40191190, 2025). "The prognostic significance of FGD3 and SUSD3 as single gene prognostic biomarker using Cox regression models in a large collection of breast cancer cohorts and TCGA cohorts has not been published." (PMID 32913979, 2017). "A study has shown that a lack of SUSD3 expression in breast cancer tissues may be an important predictor of non-response to aromatase inhibitors." (PMID 34364397, 2021).
amoebiasis (1 paper, 2025). "GSEA results revealed that SUSD3 is closely linked to immune activation processes, acting as a positive regulator of several key pathways, including IRE1-mediated unfolded protein responses, amebiasis, and proteoglycan pathways in cancer." (PMID 40191190, 2025).
autoimmune thyroid disease (1 paper, 2025). Inflammatory disease of the thyroid gland due to autoimmune responses leading to lymphocytic infiltration of the gland. "In contrast, SUSD3 was found to negatively regulate pathways such as circulating immunoglobulin complexes, immunoglobulin receptor interactions, and autoimmune thyroid disease." (PMID 40191190, 2025).
ischaemic stroke (1 paper, 2023). "And SUSD3 gene also differential expressed in patients with ischaemic stroke and matched controls." (PMID 37203300, 2023).
melanoma (1 paper, 2025). A malignant, usually aggressive tumor composed of atypical, neoplastic melanocytes. "In the GSE91061 melanoma cohort, patients with high SUSD3 expression exhibited significantly better survival rates compared to those with low SUSD3 expression." (PMID 40191190, 2025).
metastatic tumors (1 paper, 2024). "In line with previous observations, ITGB7 was expressed in primary and metastatic tumors (TCGA-SKCM) and like SUSD3 was associated with favored survival." (PMID 38386085, 2024).
systemic lupus erythematosus (1 paper, 2025). An autoimmune multi-organ disease typically associated with vasculopathy and autoantibody production. "In PAAD, SUSD3 functioned as a positive regulator of immunoglobulin receptor binding, MHC protein complex formation, and systemic lupus erythematosus." (PMID 40191190, 2025).
tumor (5 papers, 2017 to 2025). "The study examined the correlation between SUSD3 expression and immune cell infiltration, alongside its association with immunomodulatory genes, to better understand its biological relevance in tumor biology." (PMID 40191190, 2025). "The SUSD3 protein, marked by the Sushi domain, plays a key role in cancer progression, with its expression linked to tumor advancement and patient prognosis." (PMID 40191190, 2025). "The relationship between the SUSD3 gene and key immunomodulators, tumor mutational burden (TMB), and microsatellite instability (MSI) was also explored, further establishing SUSD3 as a promising biomarker for cancer immunotherapy." (PMID 40191190, 2025). "Spatial distribution analysis using the STOmics DB database also showed that SUSD3 co-localized with the tumor cell marker ANXA1 and the T cell marker CCR7 in SKCM cancer tissues, indicating spatially similar distributions." (PMID 40191190, 2025). "Using the HPA and GeneMANIA platforms, the distribution of SUSD3 protein across tissues was analyzed, while expression levels in tumor and healthy tissues were compared using The Cancer Genome Atlas data." (PMID 40191190, 2025). "The study established clear correlations between SUSD3 expression and various key cancer characteristics, including prognosis, immune regulation, immune cell infiltration, tumor microenvironment, TMB, and MSI." (PMID 40191190, 2025). "In the majority of tumor types, SUSD3 expression was positively correlated with the infiltration of B cells, CAFs, dendritic cells, CD4+ T cells, macrophages, CD8+ T cells, monocytes, NK cells, and Treg cells." (PMID 40191190, 2025). "Additionally, SUSD3 has been shown to influence cell growth and migration, thereby contributing to tumor progression." (PMID 40191190, 2025). "In the tumor microenvironment (TME), SUSD3 is predominantly expressed in monocytes/macrophages and CD4+ T cells." (PMID 40191190, 2025). "Further stratification of tumor samples into hypermethylation and hypomethylation groups revealed that patients with GBM, LGG, and LIHC tumors exhibited lower OS with increased SUSD3 methylation levels." (PMID 40191190, 2025). "Comparing top DEGs which differentiate dura-originating from tumor-originating T cells, dura T cells’ DEGs were related to T cell migration and function, such as CXCR3 and ITGAL, as well as cell motility genes SUSD3 and FGD3." (PMID 35534852, 2022). "In a specific dataset (GSE103322) containing 5,902 single cells derived from 18 patients with HINSCs, SUSD3 expression was found to be particularly evident in CD4+ T conventional cells (Tconv), cytotoxic T lymphocytes, and CD8+ T-exhausted (Tex) cells within the HINSC tumor microenvironment." (PMID 40191190, 2025). "We observed a high concordance with immune cell-related but not tumor cell-related genes (NGFR, MITF, MLANA, SLC45A2) and correlation with expression of PDCD1LG2 and SUSD3, irrespective of the side of metastasis." (PMID 38386085, 2024). "As shown in the heatmap, SUSD3 exhibited a significant negative correlation with these immune response genes in BRCA, KICH, and KIRC, while it was positively correlated with the same genes in other tumor types." (PMID 40191190, 2025).
cancer (3 papers, 2023 to 2025). A tumor composed of atypical neoplastic, often pleomorphic cells that invade other tissues. "SUSD3 expression variations in pan-cancer cohorts are closely linked to the prognosis of various malignancies." (PMID 40191190, 2025). "In our study, we confirmed that SUSD3 is closely associated with immune cells and related molecules across most cancer types." (PMID 40191190, 2025). "Initially, the OpenTarget tool was utilized to explore diseases associated with SUSD3, followed by an investigation of its expression across various cancer types using the TIMER database." (PMID 40191190, 2025). "The results were highly consistent across these endpoints, demonstrating that SUSD3 is significantly associated with the prognosis of cancer patients." (PMID 40191190, 2025). "The expression levels of SUSD3 across various cancer types were analyzed using data from the TCGA database, and the association between SUSD3 expression and cancer prognosis was examined through one-way Cox regression analysis." (PMID 40191190, 2025). "The association between SUSD3 expression and immune factors further supports its role in influencing cancer immunotherapy outcomes, making it a promising candidate for predicting patients’ responses to immunotherapies such as ICIs." (PMID 40191190, 2025). "The results showed that the expression levels of DNM1, MEIS1, and SUSD3 were associated with many cancer immune checkpoints." (PMID 38167056, 2024). "At the same time, SUSD3 was significantly associated with a better prognosis of various types of cancer (SKCM, SKCM-M, BRCA, KIPAN, MESO, SARC, LUAD)." (PMID 38167056, 2024). "In conclusion, this comprehensive pan-cancer analysis of SUSD3 has highlighted its potential as both a cancer prognostic biomarker and a predictor of immunotherapy response." (PMID 40191190, 2025). "Using siRNA technology, cancer cell lines with SUSD3 knockdown were generated to investigate the biological significance of SUSD3 and its underlying mechanisms." (PMID 40191190, 2025). "With the exception of BRCA, KICH, and KIRC, SUSD3 exhibited a positive correlation with immune-related genes in all other cancers, including MHC proteins, immunosuppressive factors, immune-activating proteins, chemokine receptors, and chemokines." (PMID 40191190, 2025). "Research indicates a strong correlation between SUSD3 expression and key cancer immunotherapy biomarkers, immune cell infiltration, and immunomodulatory factors." (PMID 40191190, 2025). "In this context, the present study highlights SUSD3 as a promising pan-cancer prognostic biomarker with the potential to predict responses to immunotherapy effectively." (PMID 40191190, 2025). "This article offers a comprehensive analysis and discussion of the role of SUSD3 across various cancer types." (PMID 40191190, 2025). "As research into SUSD3 continues to advance, it holds the potential to significantly enhance personalized cancer treatment strategies and help in the development of new therapeutic approaches targeting its related pathways." (PMID 40191190, 2025). "Based on the median expression levels of SUSD3 across various cancer types, the samples were stratified into two groups: one representing high expression and the other low expression of SUSD3." (PMID 40191190, 2025). "The TISCH and STOmics DB databases facilitated the mapping of SUSD3 expression in different cell types and its spatial relationship with cancer markers." (PMID 40191190, 2025).
cancer (continued). "Overall, these results not only underscore the potential role of SUSD3 in cancer treatment but also highlight selumetinib as a possible candidate for further clinical evaluation, possibly through its effects on the SUSD3-related pathways." (PMID 40191190, 2025). "The analysis revealed that genomic alterations in the SUSD3 gene are relatively rare across cancers, with the most common alteration occurring in DLBC, where over 4% of patients exhibit alterations, predominantly involving deep deletions." (PMID 40191190, 2025). "Next, the samples were stratified into three groups based on CNV status—WT (wild-type), Amp (amplification), and Dele (deletion)—to examine the survival implications of SUSD3 CNV across various cancers." (PMID 40191190, 2025). "Collectively, these results confirm the potential of SUSD3 as a predictive biomarker for immunotherapy response and underscore its promising role in cancer immunotherapy." (PMID 40191190, 2025). "The findings underscore the pivotal role of SUSD3 in cancer research and development, presenting new targets and therapeutic strategies for cancer treatment." (PMID 40191190, 2025). "The results indicated that in 33 different cancers, the frequency of heterozygous deletions of SUSD3 significantly exceeded that of heterozygous amplifications." (PMID 40191190, 2025). "Univariate Cox regression assessed the prognostic significance of SUSD3 expression in various cancers." (PMID 40191190, 2025). "As research continues to evolve, SUSD3 is poised to emerge as a promising target for the diagnosis and treatment of various cancer types, offering novel avenues for therapeutic intervention." (PMID 40191190, 2025). "The findings demonstrated a pronounced upregulation of SUSD3 in several cancers, including BRCA, COAD, LGG, PAAD, LUAD, READ, and STAD, in comparison to normal tissue." (PMID 40191190, 2025). "As research progresses, the significance of SUSD3 in various cancer types has become increasingly apparent, positioning it as a key player in the evolving landscape of pan-cancer research." (PMID 40191190, 2025). "The results showed that DNM1, MEIS1, and SUSD3 were differentially expressed between various cancers and normal tissues." (PMID 38167056, 2024). "The results of the pan-cancer analysis showed that MEIS1 and DNM1 were significantly highly expressed in AML; MEIS1 and SUSD3 are potential risk factors for the prognosis of AML, and DNM1 is a potential protective factor." (PMID 38167056, 2024). "To study the relationship between the expression levels of DNM1, MEIS1, and SUSD3 and the prognosis of 33 kinds of cancer, we carried out a survival correlation analysis." (PMID 38167056, 2024). "Moreover, the findings of this research offer valuable insights into the role of SUSD3 in cancer treatment, paving the way for further investigation into its therapeutic potential." (PMID 40191190, 2025). "However, to date, investigations into the role of SUSD3 have primarily focused on a single cancer type, and its broader implications across other malignancies remain inadequately explored." (PMID 40191190, 2025). "A heatmap summarizing the prognostic analysis of SUSD3 across pan-cancer datasets revealed that SUSD3 did not correlate with the prognosis of KIRC but showed significant associations with the prognosis of most other cancer types." (PMID 40191190, 2025). "These genes exhibit a strong correlation with SUSD3 and may be pivotal in the pathogenesis of cancer." (PMID 40191190, 2025). "The high expression of SUSD3 in immune cells within the TME suggests that it may serve as a potential therapeutic target capable of influencing the cancer immune response." (PMID 40191190, 2025). "Additionally, SUSD3 emerges as a reliable prognostic marker for numerous cancers, opening new avenues for further investigation into its clinical application in oncology." (PMID 40191190, 2025).